S100A6 (S100 calcium binding protein A6)
Diseases named in the same sentence as S100A6 in open-access papers (continued):
Sharing a sentence is not in itself a finding about the gene and the disease.
cognitive deficits (3 papers, 2014 to 2020). "This suggests that down-regulation of S100A6 is involved in early posttraumatic events that lead to secondary cognitive disorders while the elevation of S100A6 level in time is implicated in neuronal regeneration and repair." (PMID 32492924, 2020). "A previous study showed that a decrease in S100A6 expression in the rat hippocampus is associated with TBI-induced cognitive deficits; therefore, the increased expression at 3 month suggests a regenerative response." (PMID 30943276, 2019). "S100A6 level alterations in rat hippocampus post-TBI occurred in association with animal cognitive deficits." (PMID 24739809, 2014). "Our data seems to suggest that down-regulation of S100A6 is involved in early posttraumatic events that lead to secondary cognitive disorders." (PMID 24739809, 2014).
glaucoma (3 papers, 2017 to 2018). Increased pressure in the eyeball due to obstruction of the outflow of aqueous humor. "Lysozyme (LYZ) and S100A6 protein expressions have been linked to dry eye disease and glaucoma drug adverse effects; LYZ expression decreases while S100A6 increases in response to these conditions." (PMID 30069167, 2018). "In addition, S100A6 has been used for monitoring the response of patients to changing glaucoma treatment from preserved latanoprost to preservative-free tafluprost." (PMID 29234088, 2017).
leukemia (3 papers, 2011 to 2023). A malignant (clonal) hematologic disorder, involving hematopoietic stem cells and characterized by the presence of primitive or atypical myeloid or lymphoid cells in the bone marrow and the blood. "S100A6-mediated Akt regulation represents a target window for the development of new therapeutics specifically toward MLL-AF4 leukemia patients that may be treated with drugs that inhibit S100A6-expressing cancer cells." (PMID 32555370, 2020). "S100A6 expression is known to be upregulated in leukemia with poor prognosis and it exerts antiapoptotic effects in mixed-lineage leukemia (MLL)/AF4-positive leukemia cells." (PMID 32555370, 2020).
myocardial ischemia (3 papers, 2019 to 2023). A disorder of cardiac function caused by insufficient blood flow to the muscle tissue of the heart. "In contrast, in rat cardiac myocytes, the expression of S100A6 limited apoptosis and infarct size after myocardial ischemia-reperfusion in an experimental rat model." (PMID 37108591, 2023). "Myocardial ischemia or necrosis promotes the production of inflammatory factors such as S100B, S100A6, S100P, and RAGE in the infarct area; activates the S100-RAGE axis; and induces the increase of inflammatory cytokines." (PMID 31275446, 2019). "Mofid and colleagues reported that S100A6 overexpression attenuated myocardial ischemia reperfusion injury." (PMID 31440382, 2019).
Obesity (3 papers, 2020 to 2024). Accumulation of substantial excess body fat. "We observed significant upregulation of genes such as Cyp11a1, Fdx1, Flt1, Gm2a, and S100a6 in the G05 subpopulation under the influence of obesity." (PMID 38956667, 2024). "In memory T cells, expression of Lgals1 and S100a6 genes was upregulated by HFD-induced obesity." (PMID 32785175, 2020).
pancreatic ductal adenocarcinoma (3 papers, 2011 to 2021). An infiltrating adenocarcinoma that arises from the epithelial cells of the pancreas. "In Badea’s dataset, S100A6 was found higher expressed in pancreatic ductal adenocarcinoma compared to normal tissues (fold change = 5.92)." (PMID 34804125, 2021). "S100A6 is reported to be upregulated in a number of cancers, including lung, colorectal, skin, gastric, pancreatic ductal adenocarcinoma and other epithelial cancers." (PMID 25799022, 2015). "This is further supported by the presence of S100A6 protein in the cytoplasm and nuclei of lung, skin, and pancreatic ductal adenocarcinoma cells." (PMID 21305022, 2011).
pancreatitis (3 papers, 2021 to 2023). Inflammation of the pancreas. "Compared with pancreatitis-affected epithelial or normal cells, S100A6 is overexpressed in IDC and IPMN cells, supporting the idea that measurement of S100A6 might help distinguish PDAC or IPMN from CP." (PMID 34527585, 2021).
pterygium (3 papers, 2009 to 2022). A wedge-shaped fibrovascular lesion arising from the bulbar conjunctiva and extending to the cornea. "In pterygium tissue, S100A6 expression increased 2.30 fold, S100A8 increased 3.36 fold, and S100A9 increased 4.01 fold relative to normal conjunctiva." (PMID 19223989, 2009). "The differential localization of S100A4 and S100A6 demonstrated in our study raises the possibility of a stem cell defect in pterygium." (PMID 19223989, 2009). "S100A6 expression was strong in the superficial layer of pterygium epithelium but relatively weaker in the suprabasal and superficial cells of normal conjunctiva epithelium." (PMID 19223989, 2009). "S100A6 was detected in the membrane and cytoplasm of the superficial epithelial cells as well as some suprabasal cells of normal conjunctival epithelium but was found only in the superficial layer of pterygium epithelium." (PMID 19223989, 2009). "Higher expression levels of S100A6, S100A8, and S100A9 were observed in the pterygium tissue when compared to normal conjunctiva and it has been postulated that these proteins may be associated with the pterygium formation." (PMID 30673862, 2019). "Our investigation revealed that S100A4, S100A6, S100A8, S100A9, and S100A11 are expressed in both the normal and pterygium epithelia." (PMID 19223989, 2009). "Immunofluorescent staining detected the presence of S100A4, S100A6, S100A8, S100A9, and S100A11 in normal human conjunctival and pterygium epithelia." (PMID 19223989, 2009). "Western blot and RT–PCR confirmed the presence of S100A4, S100A6, S100A8, S100A9, and S100A11 in pterygium and conjunctiva tissue." (PMID 19223989, 2009). "S100A4, S100A6, S100A8, S100A9, and S100A11 gene transcripts were detected in conjunctiva and pterygium tissues." (PMID 19223989, 2009). "Higher levels of S100A6, S100A8, and S100A9 expressions were detected in the pterygium tissue relative to normal conjunctiva." (PMID 19223989, 2009). "However, S100A6, S100A8, and S100A9 transcripts were upregulated (p<0.05) in pterygium relative to normal conjunctiva." (PMID 19223989, 2009). "However, expression of S100A6, S100A8, and S100A9 were markedly greater in the pterygium tissue compared to the uninvolved conjunctival tissue." (PMID 19223989, 2009). "In summary, a change in level of expression was detected in S100A6, S100A8, and S100A9 in pterygium tissue relative to the normal conjunctiva." (PMID 19223989, 2009).
thyroid cancer (3 papers, 2020 to 2024). "In vitro cell experiments demonstrated the promising modulation of thyroid cancer biomarker genes S100A6 and ARID1A by HA/CMCS-CP1@paclitaxel." (PMID 38844812, 2024). "In the paper, the authors demonstrated that the expression patterns of S100A6 in thyroid carcinoma are unique compared with those of other carcinomas, and over-expression in thyroid carcinoma." (PMID 34149811, 2021). "As to TCHA(Thyroid carcinoma), The S100A6 gene selected by our method is a protein-coding gene." (PMID 34149811, 2021). "S100A6 gene can be used as a biomarker of Thyroid carcinoma." (PMID 34149811, 2021). "It has been previously reported that the S100 proteins S100A2, S100A4, S100A6, and S100A9 are upregulated in thyroid cancer and that these subfamily members are involved in the progression of cancer in different ways." (PMID 32015423, 2020).
adenoma (2 papers, 2009 to 2021). A neoplasm arising from the epithelium. "In the advanced adenoma group, differences between the healthy mucosa and adenomatous tissue were found in S100A6 (p = 0.002), S100A8 (p = 0.002), S100A9 (p = 0.021) and S100A11 (p = 0.029)." (PMID 33466593, 2021). "Our study also showed that there was a further significantly increased expression of S100A6 in the tissue of advanced colorectal adenoma patients compared to the normal healthy mucosa of those with an advanced adenoma." (PMID 33466593, 2021). "Nearly 85% of benign adenomas showed positive S100A6 reactivity as well; the labeling intensity was comparable with that of malignant OVCA." (PMID 19888321, 2009). "Our study focused on the assessment of the gene expression of S100A6 and confirmed that the mRNA for S100A6 increased significantly in the healthy mucosa of those who had an advanced adenoma in their colon or rectum at the time of the study compared to controls." (PMID 33466593, 2021).
cardiac hypertrophy (2 papers, 2018). "It has been stated that S100A6 abolishes cardiomyocyte overgrowth induced by various hypertrophic factors and reduces cardiac hypertrophy in mice exposed to I/R heart injury." (PMID 30286717, 2018). "In the past decade researches have confirmed the involvement of S100A6 protein in cardiac hypertrophy." (PMID 30286717, 2018). "Cannabinoids and protein S100A6 perform a significant role in the process of cardiac hypertrophy." (PMID 30482253, 2018).
Cirrhosis (2 papers, 2009 to 2024). A chronic disorder of the liver in which liver tissue becomes scarred and is partially replaced by regenerative nodules and fibrotic tissue resulting in loss of liver function. "In the present study, the expression level of S100a10, S100a11, S100a6, S100a8 and S100a9 increased from cirrhosis to metastatic process when compared with the normal liver." (PMID 19638242, 2009).
clear cell carcinoma (2 papers, 2009 to 2025). "High S100A6 positive incidence (over 80%) was observed in all malignant types of OVCA with the exception of clear cell carcinoma, of which only 2 out of 4 specimens were S100A6 positive." (PMID 19888321, 2009).
cognitive decline (2 papers, 2014 to 2025). "In conclusion, a reduction in S100A6 may be one of the early events that lead to secondary cognitive decline after TBI, and its subsequent elevation is tightly linked with cognitive improvement." (PMID 24739809, 2014).
COVID-19 (2 papers, 2022 to 2023). A disease caused by infection with severe acute respiratory syndrome coronavirus 2. "They found that S100A6, S100A9, and S100A12 were predictors of severe AP, and that a specific subtype of neutrophils was responsible for COVID-19-induced AP." (PMID 36830652, 2023). "Finally, correlation between S100A6, S100B, S100A8, S100A9, S100A12, and S100P and COVID-19 pathogenesis is discussed." (PMID 35892571, 2022).
ependymoma (2 papers, 2008 to 2022). A WHO grade II, slow growing tumor of children and young adults, usually located intraventricularly. "S100A6 is significantly associated with paediatric ependymoma arising in the supratentorial compartment and S100A4 strongly correlates with patients aged less than 3 years at diagnosis." (PMID 18781180, 2008). "S100A4 and S100A6 are clearly differentially expressed in paediatric ependymoma and can be used to distinguish clinically and biologically relevant subgroups." (PMID 18781180, 2008). "S100A6 was also identified as one of the most highly expressed genes in ependymoma when compared with ‘normal’ brain." (PMID 18781180, 2008). "In ependymoma, we have clearly demonstrated that S100A6 is differentially expressed in tumours arising in different locations of the brain, and is significantly associated with supratentorial tumours (P<0.001)." (PMID 18781180, 2008). "A second member of the S100 family, S100A6, was identified with one of the highest differences between ependymoma and normal brain of 27.1." (PMID 18781180, 2008). "Candidates (CHI3L1, S100A10, S100A4, S100A6 and S100A2) were validated using immunohistochemistry on a tissue microarray of 74 paediatric ependymoma." (PMID 18781180, 2008). "Protein expression levels of S100A10, S100A6, S100A4 and S100A2 were determined by immunohistochemistry using an independent cohort of seventy-four primary paediatric ependymoma arrayed on a tissue microarray." (PMID 18781180, 2008). "In conclusion, this study provides evidence that S100A6 and S100A4 are differentially expressed in clinically relevant subgroups, and also demonstrates a link between CHI3L1 protein expression and necrosis in intracranial paediatric ependymoma." (PMID 18781180, 2008).
epidermoid carcinoma (2 papers, 2020 to 2021). "The S100a6 competes with Hsp90 for binding to sgt1 and it influences the translocation of Sgt1 in human epidermoid carcinoma cells during HS." (PMID 32183190, 2020).
gastric tumor (2 papers, 2012 to 2025). "The expression of annexin II and S100A6 mRNA differ significantly among gastric tumor tissue and matched non-cancerous gastric mucosa." (PMID 22681645, 2012). "The mRNA expressions of annexin II and S100A6 in gastric tumor tissues and corresponding non-tumor tissues were analyzed using qRT-PCR in a total of 40 pairs of matched tissue specimens." (PMID 22681645, 2012).
intrahepatic cholangiocarcinoma (2 papers, 2019 to 2023). A carcinoma that arises from the intrahepatic bile duct epithelium in any site of the intrahepatic biliary tree. "S100A6 was shown to promote the proliferation of intrahepatic cholangiocarcinoma cells and of cervical cells via activating the p38/MAPK and PI3K/Akt pathways, respectively." (PMID 31850060, 2019). "S100A6 may also be a prognostic marker and potential therapeutic target for patients with intrahepatic cholangiocarcinoma (ICC)." (PMID 37670392, 2023).
lung adenocarcinoma (2 papers, 2021). A carcinoma that arises from the lung and is characterized by the presence of malignant glandular epithelial cells. "Our single-cell analysis indicated that expression of SPP1 and S100A6 were associated with global hypomethylation of lung adenocarcinoma cells." (PMID 34857857, 2021). "By differential expression analysis and LASSO logistic regression analysis we constructed an 8-gene (IKBKB, LTBR, MIF, PPARD, PPIA, PSME3, S100A6, SEMA4B) based risk score model to predict lymph node metastasis in lung adenocarcinoma." (PMID 34109216, 2021).
multiple myeloma (2 papers, 2022 to 2024). "The results suggest that three genes, CRIP1, HIST1H1C and RNF125, are significantly overexpressed in myeloma cell lines and may contribute to the poor prognosis in malignant plasma cell samples, whereas C1orf56 and S100A6 may contribute to the poor prognosis in microenvironmental cell samples." (PMID 38278930, 2024).
muscular dystrophies (2 papers, 2008 to 2022). "Upregulation of S100A6 expression was seen also in LGMD2B and as in other muscular dystrophies, the structural defect causes a general membrane instability that leads to an altered uptake of calcium ions into the muscle fibers." (PMID 19015733, 2008). "Together with the involvement of S100A6 in LMNA-related muscular dystrophy from our study, altered calcium cycling might be a common disturbance due to LMNA mutations, although the involved calcium regulators may differ in different subtypes of laminopathy." (PMID 36555163, 2022).
myocardial infarction (2 papers, 2019 to 2023). Gross necrosis of the myocardium, as a result of interruption of the blood supply to the area, as in coronary thrombosis. "It has been reported that conditional overexpression of S100A6 in cardiac myocytes can mitigate hypertrophy and apoptosis of myocytes after myocardial infarction." (PMID 31440382, 2019). "However, after the induction of myocardial infarction in rats, the expression of s100A6 was increased due to cardiomyocyte damage, and serum level of S100A6 protein was correlated with infarct size." (PMID 37217870, 2023).
non-small cell lung carcinoma (2 papers, 2009 to 2021). A group of at least three distinct histological types of lung cancer, including non-small cell squamous cell carcinoma, adenocarcinoma, and large cell carcinoma. "A recent report also showed that S100A6 was largely down-regulated in tissues from non-small cell lung cancer patients compared to control tissues." (PMID 34769496, 2021).
ovarian tumor (2 papers, 2025 to 2026). "METHODS: The impact of cytoplasmic and nuclear S100A6 expression on overall survival and clinicopathological criteria was investigated in 462 ovarian tumours by immunohistochemistry." (PMID 41673585, 2026).
papillary carcinoma (2 papers, 2021 to 2023). A malignant epithelial neoplasm characterized by a papillary growth pattern. "Accurate diagnosis of thyroid tumors is challenging, and S100A6 plays a potential auxiliary role in the differentiation between follicular thyroid tumors and papillary thyroid carcinomas." (PMID 37670392, 2023). "MALDI-IMS proteomics has shown that S100A6, S100A10, and thioredoxin can be used for risk stratification of the metastatic potential of papillary thyroid carcinoma." (PMID 37670392, 2023).
periodontitis (2 papers, 2022 to 2025). An acute or chronic inflammatory process that affects the tissues that surround and support the teeth. "Moreover, S100-P and S100-A6 were also found to be upregulated, as in previous studies, although their possible relationship with periodontitis has not yet been discovered." (PMID 40384977, 2025).
Pleural effusion (2 papers, 2009 to 2023). The presence of an excessive amount of fluid in the pleural cavity. "For example, plasma and pleural effusions from NSCLC patients with high levels of the S100A6 protein—a member of the S100 family with pro-apoptotic function—presented longer survival time compared with S100A6-negative cases." (PMID 36768828, 2023).
Sjögren’s Syndrome (2 papers, 2016 to 2023). "Although, we did not collect samples for quantification of mRNA in whole blood, our results accord with previously published gene expression studies on the RNF5 and the S100A6 in peripheral blood from RA patients and patients with Sjögren’s syndrome." (PMID 27909437, 2016). "The S100A6 is also overexpressed in salivary glandular epithelial cells in patients with Sjögren’s syndrome." (PMID 27909437, 2016).
acute coronary syndrome (1 paper, 2018). Signs and symptoms related to acute ischemia of the myocardium secondary to coronary artery disease. "Increased S100A6 serum levels have been found in patients with acute coronary syndrome and in the rat model of MI." (PMID 30286717, 2018).
amyloid (1 paper, 2019). "Given the high zinc-binding capacity of S100A6, we proposed that the elevated expression of S100A6 around amyloid plaques in patients with AD might play an important role in inhibiting Aβ aggregation and plaque formation through competition for zinc." (PMID 31440382, 2019).
atherosclerosis (1 paper, 2022). A disease characterized by the build-up of fatty material and calcium deposition in the arterial wall resulting in partial or complete occlusion of the arterial lumen. "Although other genes in the module are not involved in the fluid shear stress and atherosclerosis pathway, S100a6 and Ifitm3 are known to regulate PI3K signaling, a sub-pathway of the fluid shear stress and atherosclerosis pathway." (PMID 36207684, 2022).
bacterial sepsis (1 paper, 2025). "The eight differentially expressed genes (DEGs) as key diagnostic markers for bacterial sepsis: FTH1, B2M, NAMPT, KLF6, SRGN, S100A6, S100A9, and S100A8." (PMID 41303672, 2025).
brain tumour (1 paper, 2008). "S100A10 and S100A6 showed the highest mean expression across the six brain tumour types of 43.6 and 41.7 tags, respectively." (PMID 18781180, 2008).
carcinomas of colon (1 paper, 2009). "With respect to S100A6, its expression is normally found in fibroblasts and epithelial cells, and elevated S100A6 has been reported in a number of human cancer types including carcinomas of colon, pancreas, breast, ovary, lung and thyroid gland." (PMID 19888321, 2009).
clear cell ovarian carcinoma (1 paper, 2009). "All OVCA cells tested, except OVCAR-4 and the cell line derived from clear cell ovarian carcinoma (ACI-89-2), expressed S100A6 above background level (normal ovary)." (PMID 19888321, 2009).
colorectal tumor (1 paper, 2022). "S100A4 and S100A6 play an important role in tumor metastases, including colorectal tumor metastasis." (PMID 36523772, 2022).